DAB2 (DAB adaptor protein 2)
Description:
Adapter protein that functions as a clathrin-associated sorting protein (CLASP) required for clathrin-mediated endocytosis of selected cargo proteins. Can bind and assemble clathrin, and binds simultaneously to phosphatidylinositol 4,5-bisphosphate (PtdIns(4,5)P2) and cargos containing non-phosphorylated NPXY internalization motifs, such as the LDL receptor, to recruit them to clathrin-coated pits. Can function in clathrin-mediated endocytosis independently of the AP-2 complex. Involved in endocytosis of integrin beta-1; this function seems to redundant with the AP-2 complex and seems to require DAB2 binding to endocytosis accessory EH domain-containing proteins such as EPS15, EPS15L1 and ITSN1. Involved in endocytosis of cystic fibrosis transmembrane conductance regulator/CFTR. Involved in endocytosis of megalin/LRP2 lipoprotein receptor during embryonal development. Required for recycling of the TGF-beta receptor. Involved in CFTR trafficking to the late endosome. Involved in several receptor-mediated signaling pathways. Involved in TGF-beta receptor signaling and facilitates phosphorylation of the signal transducer SMAD2. Mediates TFG-beta-stimulated JNK activation. May inhibit the canoniocal Wnt/beta-catenin signaling pathway by stabilizing the beta-catenin destruction complex through a competing association with axin preventing its dephosphorylation through protein phosphatase 1 (PP1). Sequesters LRP6 towards clathrin-mediated endocytosis, leading to inhibition of Wnt/beta-catenin signaling. May activate non-canonical Wnt signaling. In cell surface growth factor/Ras signaling pathways proposed to inhibit ERK activation by interrupting the binding of GRB2 to SOS1 and to inhibit SRC by preventing its activating phosphorylation at 'Tyr-419'. Proposed to be involved in modulation of androgen receptor (AR) signaling mediated by SRC activation; seems to compete with AR for interaction with SRC. Plays a role in the CSF-1 signal transduction pathway. Plays a role in cellular differentiation. Involved in cell positioning and formation of visceral endoderm (VE) during embryogenesis and proposed to be required in the VE to respond to Nodal signaling coming from the epiblast. Required for the epithelial to mesenchymal transition, a process necessary for proper embryonic development. May be involved in myeloid cell differentiation and can induce macrophage adhesion and spreading. May act as a tumor suppressor.
Synonyms: DOC-2; DOC2
Tractability: Antibody: its Gene Ontology location is reachable by antibodies, with high confidence; the Human Protein Atlas places it where antibodies can reach. PROTAC: ubiquitination databases record sites on it; its protein half-life has been measured.
Gene: Protein-coding gene on chromosome 5 (39,371,675 to 39,462,300, reverse strand). Ensembl gene ENSG00000153071.
Subcellular location: Cytoplasm; Cytoplasmic vesicle, clathrin-coated vesicle membrane; Membrane, clathrin-coated pit
Subcellular location (Human Protein Atlas): Plasma membrane; Vesicles; Nucleoli fibrillar center
Pathways (Reactome):
Vesicle-mediated transport: Cargo recognition for clathrin-mediated endocytosis; Clathrin-mediated endocytosis; Formation of annular gap junctions; Gap junction degradation
Gene Ontology:
Molecular function: cargo receptor activity; clathrin adaptor activity; protein binding; SMAD binding; low-density lipoprotein particle receptor binding
Biological process: integrin-mediated signaling pathway; leading edge cell differentiation; negative regulation of androgen receptor signaling pathway; negative regulation of apoptotic process; negative regulation of canonical Wnt signaling pathway; negative regulation of protein localization to plasma membrane; negative regulation of transcription by RNA polymerase II; positive regulation of cell migration; positive regulation of clathrin-dependent endocytosis; positive regulation of early endosome to late endosome transport; positive regulation of endocytosis; positive regulation of epithelial to mesenchymal transition; positive regulation of proteasomal ubiquitin-dependent protein catabolic process; positive regulation of SMAD protein signal transduction; positive regulation of transcription by RNA polymerase II; positive regulation of Wnt signaling pathway, planar cell polarity pathway; transforming growth factor beta receptor signaling pathway; receptor-mediated endocytosis; cellular response to epidermal growth factor stimulus; cellular response to transforming growth factor beta stimulus; clathrin coat assembly; negative regulation of cell growth; negative regulation of epithelial cell proliferation; negative regulation of ERK1 and ERK2 cascade; negative regulation of neuron projection development; and 5 more
Cellular component: clathrin-coated pit; clathrin-coated vesicle; focal adhesion; plasma membrane; cytoplasm; cytosol; lysosomal membrane; clathrin-coated vesicle membrane; perinuclear region of cytoplasm
Genetic constraint (gnomAD): Loss-of-function variants: 18 observed, 55.71 expected, observed/expected ratio (o/e) 0.32, 90% interval 0.22 to 0.48. The upper end of that interval is the gene's LOEUF score, 0.48, which puts it in group 2 of 6, group 1 being the genes least tolerant of losing a copy. Missense variants: 719 observed, 830.28 expected, observed/expected ratio (o/e) 0.87, 90% interval 0.81 to 0.92. Synonymous variants: 302 observed, 315.81 expected, observed/expected ratio (o/e) 0.96, 90% interval 0.87 to 1.05.
Homologues: Orthologues: chimpanzee DAB2 (99% identical), macaque DAB2 (97% identical), dog DAB2 (90% identical), pig DAB2 (88% identical), rabbit DAB2 (86% identical), guinea pig Dab2 (85% identical), mouse Dab2 (84% identical), rat Dab2 (83% identical), guinea pig Dab2 (82% identical), tropical clawed frog dab2 (61% identical), zebrafish DAB2 (46% identical), zebrafish dab2 (34% identical), and 10 more. Paralogues in human: DAB1 (27% identical), NUMB (16% identical), NUMBL (14% identical), NOS1AP (9% identical), LDLRAP1 (7% identical), MAPK8IP1 (7% identical), FAM43A (6% identical), FAM43B (6% identical), MAPK8IP2 (6% identical), GULP1 (4% identical), C1orf226 (2% identical).
Diseases named in the same sentence as DAB2 in open-access papers:
DAB2 is named in the same sentence as 114 diseases in open-access papers, as found by Europe PMC text mining. Sharing a sentence is not in itself a finding about the gene and the disease. The quoted sentences say what the papers report.
ovarian carcinoma (34 papers, 2005 to 2024). A malignant neoplasm originating from the surface ovarian epithelium. "Our findings suggest that TAMs contribute to the high DAB2 positive cells in the cancer-associated stroma found to be associated with reduced ovarian cancer survival." (PMID 37815603, 2023). "Our findings show that DAB2 is associated with ovarian cancer metastasis, HA signaling molecules, EMT and poor prognosis." (PMID 37815603, 2023). "Stromal DAB2 immunostaining was significantly increased in matched ovarian cancer tissues at relapse compared to diagnosis and associated with reduced survival." (PMID 37815603, 2023). "This suggests a potential relationship between loss of GATA6 and DAB2 expression in initiation of ovarian cancer." (PMID 36614139, 2022). "Systematic analysis of a large panel of ovarian carcinomas showed that loss of Dab2 expression occurs in about 90% of ovarian cancer, and is an early event in ovarian tumorigenicity." (PMID 27933291, 2016). "The loss of expression of Dab2 in ovarian cancer and growth regulatory properties in cell culture studies led to the suggestion that Dab2 is a tumor suppressor in ovarian cancer." (PMID 24168030, 2013). "The loss of Dab2 correlates well with morphological changes, specifically the transition from a simple epithelial monolayer to a multiple layered neoplasm in ovarian cancer." (PMID 24168030, 2013). "DAB2 which is a regulator of ovarian carcinoma and has been implicated in prostate and breast cancer is a common gene in the top ten genes selected using Euclidean distance and Mutual information." (PMID 22867264, 2012). "The loss of GATA4 precedes the loss of GATA6 (and Dab2), similar to the observation in the pre-neoplastic ovarian epithelia adjacent to ovarian carcinomas, where GATA4 is often lost prior to GATA6." (PMID 19649254, 2009). "The DAB2 gene has been identified as a potent tumor suppressor gene in prostate and ovarian carcinoma, and loss of expression of this gene has been associated with the transition of ovarian epithelial cells to premalignant states." (PMID 16004614, 2005). "A suggestive observation is that the loss of Dab2 expression occurs in an epithelial layer, and correlates closely with morphological transformation from a benign monolayer to malignant multiple layered ovarian cancer." (PMID 27933291, 2016). "In sum, all the genes in this module are associated with various cancers and cell death, so DAB2 may regulate ovarian cancer progression by mediating cell death signaling pathway, which may be a novel biomarker in clinical practice." (PMID 25861644, 2015). "Thus, loss of Dab2 results in epithelial depolarization and subsequent disorganization, as found in ovarian carcinomas and early embryos." (PMID 24168030, 2013). "Thus, loss or reduction of Dab2 expression may lead to the anchorage-independent proliferation of mammary and ovarian cancer cells." (PMID 25360623, 2014). "DAB2 was initially identified as a novel cDNA fragment downregulated in ovarian cancer cell lines compared to normal ovarian cell lines." (PMID 37815603, 2023). "To further investigate the role of DAB2 in ovarian cancer progression, we utilized online datasets to assess the relationship of DAB2 expression with EMT markers and CSC markers in ovarian cancer cell lines and tissues." (PMID 37815603, 2023). "We highlight a complex relationship of both pro-tumorigenic and tumor suppressive functions of DAB2 in ovarian cancer." (PMID 37815603, 2023). "Future studies need to assess if demethylation treatments will also be effective at promoting DAB2 expression and reducing ovarian cancer proliferation and migration." (PMID 37815603, 2023). "We observed a positive relationship between DAB2 expression and macrophages in ovarian cancer tissues via online expression data and the TIMER dataset." (PMID 37815603, 2023). "Consistent with previous literature, DAB2 has inhibitory effects on ovarian cancer cell metabolism, motility and invasion." (PMID 37815603, 2023).
ovarian carcinoma (continued). "We found disabled-2 (DAB2) protein levels were up-regulated by 1000 kDa HA in ES-2 ovarian cancer cells mixed with ES-2 cells overexpressing NICD3 (ratio 1:3) and two HGSOC cell lines (OVCAR3 and OV90)." (PMID 37815603, 2023). "In another independent dataset (GSE2109), DAB2 expression was significantly increased in metastatic ovarian cancer tissues compared to primary ovarian cancer tissues for all ovarian cancer subtypes (***p = 0.0009) and for HGSOC tissues (***p = 0.0001)." (PMID 37815603, 2023). "Further studies including co-culture experiments with TAMs and ovarian cancer cells are required to further scrutinize the role of DAB2 in the tumour microenvironment." (PMID 37815603, 2023). "The proportion of DAB2 positive macrophages was significantly increased in metastatic ovarian cancer tissues compared to primary cancers." (PMID 37815603, 2023). "DAB2 expression was significantly decreased in ovarian cancer and FT compared to OSE (****p < 0.0001)." (PMID 37815603, 2023). "DAB2 was downregulated in ovarian cancer compared to normal tissues but increased in metastatic ovarian tumors compared to primary tumors." (PMID 37815603, 2023). "We report disabled-2 (DAB2) as a novel protein regulated by 1000 kDa HA and further investigated its role in ovarian cancer." (PMID 37815603, 2023). "DAB2 was positively correlated with M1 and M2 macrophages in ovarian cancer tissues and there was a significant increase in DAB2 positive macrophages in tumor associated stroma of metastatic ovarian cancer compared to matched primary tissues." (PMID 37815603, 2023). "We utilized online databases and independent tissue cohorts to further examine the relationship between DAB2 and ovarian cancer progression." (PMID 37815603, 2023). "DAB2 was downregulated in ovarian cancer compared to normal OSE and high DAB2 expression was associated with poor patient outcome." (PMID 37815603, 2023). "DAB2 was shown to regulate TGFβ clathrin mediated endocytosis of TGFβRI in ES-2 ovarian cancer cells." (PMID 36614139, 2022). "One of the initial studies which identified DAB2, found its expression was lost in 90% of ovarian cancer cell lines." (PMID 36614139, 2022). "DAB2 overexpression promotes cell death in ovarian cancer cells (OVCAR3) in normal tissue culture conditions, however when grown on a basement membrane, the inhibitory effect of DAB2 overexpression was reversed." (PMID 36614139, 2022). "In fact, a short mRNA fragment of Dab2 was initially identified due to its selective absence from ovarian cancer cell lines and was accordingly coined “differentially expressed in ovarian cancer” (DOC-2)." (PMID 31671891, 2019). "Estrogen suppression of Dab2 was reproducible in vivo and across many cell types including mouse oviductal epithelium and primary cultures of human ovarian cancer cells." (PMID 29196616, 2017). "In ovarian cancer, excessive miR-187 promotes tumor progression through by disabled homolog 2 (DAB2), inhibiting epithelial–mesenchymal transition." (PMID 28968959, 2017). "In ovarian cancer, miR-187 regulates tumor progression through targeting Disabled homolog-2 (Dab2), which resulted in inhibition of epithelial-mesenchymal transition." (PMID 27329595, 2016). "In ovarian cancer low DAB2 levels correlate with poor outcome, but very low levels that inhibit EMT correlate with a better prognosis." (PMID 23213280, 2012). "The observations from human ovarian cancer tissues suggests that loss of GATA4 expression often precedes the loss of GATA6, and the loss of GATA6, correlated with the loss of Dab2, associates with epithelial morphological transformation." (PMID 19649254, 2009). "Dab2 was first identified as DOC-2 which is differentially expressed in ovarian carcinoma and cell lines." (PMID 18680569, 2008).
ovarian carcinoma (continued). "DAB2 is considered a tumour suppressor since its expression is down-regulated in ovarian carcinomas and in some established breast cancer cell lines, and up-regulated during megakaryocyte differentiation." (PMID 16626496, 2006). "Disabled homolog 2 (DAB2) was firstly reported low expressed in ovarian cancer in 1994." (PMID 38481347, 2024). "Finally, although the anticancer effect of DAB2, which is common in all three cancer tissues, was first reported in ovarian cancer, DAB2 is regulated by non-coding RNAs in distinct cancer types." (PMID 38627780, 2024). "Together these results suggest the effect of HA on DAB2 expression in ovarian cancer may be dependent on Notch3." (PMID 37815603, 2023). "Interestingly, DAB2 expression was significantly increased in metastatic ovarian cancer compared to primary ovarian cancer tissue (**p = 0.0055)." (PMID 37815603, 2023). "We went on to further explore the role of DAB2 in ovarian cancer." (PMID 37815603, 2023). "In the ovarian cancer tissues, further significant positive correlations were observed between DAB2 and CSC markers (CD34, ALDH1A1, CD117 (Kit)) and mesenchymal markers (MMP9, SNAI1 and MMP3) and negative correlations with mesenchymal markers (CDH2, FOXC2 and SOX10)." (PMID 37815603, 2023). "Likewise, H3K27ac modification around the GATA6 and DAB2 loci was reduced in ovarian cancer cell lines." (PMID 37779141, 2023). "We demonstrated there was a significant increase in DAB2+ TAMs in metastatic compared to matched primary ovarian cancer tissue that may aid tumour progression." (PMID 37815603, 2023). "Interestingly, our analysis found DAB2 to be enhanced in metastatic compared to primary ovarian cancer tissues, particularly in the stroma." (PMID 37815603, 2023). "Interestingly, DAB2 was increased in metastatic ovarian cancer tissues compared to primary disease and positively associated with EMT and CSC markers." (PMID 37815603, 2023). "This study identified DAB2 as a novel protein regulated by 1000 kDa HA in ovarian cancer." (PMID 37815603, 2023). "DAB2 is an established tumor suppressor, particularly in ovarian cancer." (PMID 37815603, 2023). "Our findings highlight that DAB2 has a direct tumor suppressive role on ovarian cancer cells." (PMID 37815603, 2023). "In ovarian cancer, the percentage of tumours with positive staining for DAB2 ranged from 0–26%." (PMID 36614139, 2022). "Dab2 was reported to be a target of miR-187 in ovarian cancers." (PMID 27542258, 2016). "Full length Dab2 cDNAs were first isolated from a mouse macrophage cell line, and a fragment was also identified in another study as a gene that is expressed in human ovarian surface epithelial cells but lost in ovarian carcinomas." (PMID 27933291, 2016). "miR-187 also represses the tumor-suppressor gene disabled homolog-2 (Dab2) in ovarian cancers." (PMID 27542258, 2016). "Additional experiments further substantiated Dab2 to be a tumor suppressor in ovarian cancer." (PMID 25360623, 2014). "Next, to validate whether the downregulated genes, such as MAF, GATA6, and DAB2, are affected by epigenetic dysregulation, we treated ovarian cancer cell lines with a pan-HDAC inhibitor, TSA, which mechanistically augments transcriptionally active histone modification." (PMID 37779141, 2023). "Interestingly, 100% of mucinous tumours maintained DAB2 staining, suggesting DAB2 expression and function may vary between different ovarian cancer subtypes." (PMID 36614139, 2022). "DAB2 has previously been found to reduce cell proliferation and in vivo tumorigenicity in SKOV3 ovarian cancer cells." (PMID 37815603, 2023).